SLC7A11 (solute carrier family 7 member 11)
Description:
Heterodimer with SLC3A2, that functions as an antiporter by mediating the exchange of extracellular anionic L-cystine and intracellular L-glutamate across the cellular plasma membrane. Provides L-cystine for the maintenance of the redox balance between extracellular L-cystine and L-cysteine and for the maintenance of the intracellular levels of glutathione that is essential for cells protection from oxidative stress (By similarity). The transport is sodium-independent, electroneutral with a stoichiometry of 1:1, and is drove by the high intracellular concentration of L-glutamate and the intracellular reduction of L-cystine. Acts as an inhibitor of ferroptosis by mediating the import of L-kynurenine leading to anti-ferroptotic signaling propagation required to maintain L-cystine and glutathione homeostasis. Also inhibits ferroptosis by acting as an atypical proton transporter that mediates a slow proton efflux from lysosomes via cystine and glutamate flux. Glutamate and cystine contain side-chain groups that are protonatable in the physiological range of lysosomal pH and cytosolic pH, respectively, enabling a slow lysosomal proton leak through a substrate-as-proton mechanism. Moreover, mediates N-acetyl-L-cysteine uptake into the placenta leading to subsequently down-regulation of pathways associated with oxidative stress, inflammation and apoptosis. In vitro can also transport L-aspartate. May participate in astrocyte and meningeal cell proliferation during development and can provide neuroprotection by promoting glutathione synthesis and delivery from non-neuronal cells such as astrocytes and meningeal cells to immature neurons (By similarity). Controls the production of pheomelanin pigment directly (By similarity).
Synonyms: xCT; CCBR1
Tractability: Small molecule: a structure with a bound ligand is known; a high-quality ligand is known. Antibody: UniProt places it where antibodies can reach, with high confidence; its Gene Ontology location is reachable by antibodies, with high confidence; UniProt predicts a signal peptide or a membrane-spanning region. PROTAC: UniProt records ubiquitination sites on it; ubiquitination databases record sites on it; its protein half-life has been measured; a small molecule that binds it is known.
Target class: Transporter; SLC07 Cationic amino acid transporter/glycoprotein-associated family; Electrochemical transporter; SLC03 and SLC07 families of heteromeric amino acid transporters (HATs); SLC superfamily of solute carriers
Gene: Protein-coding gene on chromosome 4 (138,164,097 to 138,242,349, reverse strand). Ensembl gene ENSG00000151012.
Subcellular location: Cell membrane; Lysosome membrane; Cell projection, microvillus membrane
Subcellular location (Human Protein Atlas): Vesicles
Pathways (Reactome):
Cellular responses to stimuli: NFE2L2 regulating anti-oxidant/detoxification enzymes
Hemostasis: Basigin interactions
Transport of small molecules: Amino acid transport across the plasma membrane
Gene Ontology:
Molecular function: cystine:glutamate antiporter activity; L-kynurenine transmembrane transporter activity; leak channel activity; protein binding; proton channel activity; transmembrane transporter activity
Biological process: amino acid import across plasma membrane; L-cystine transport; L-glutamate transmembrane transport; L-kynurenine transmembrane transport; lysosomal lumen pH elevation; negative regulation of ferroptosis; proton transmembrane transport; response to toxic substance; amino acid transmembrane transport; amino acid transport; regulation of programmed cell death; transmembrane transport
Cellular component: cell surface; lysosomal membrane; plasma membrane; transmembrane transporter complex; membrane; apical part of cell; astrocyte projection; brush border membrane; microvillus membrane
Genetic constraint (gnomAD): Loss-of-function variants: 17 observed, 30.25 expected, observed/expected ratio (o/e) 0.56, 90% interval 0.38 to 0.84. The upper end of that interval is the gene's LOEUF score, 0.84, which puts it in group 3 of 6, group 1 being the genes least tolerant of losing a copy. Missense variants: 392 observed, 456.63 expected, observed/expected ratio (o/e) 0.86, 90% interval 0.79 to 0.93. Synonymous variants: 153 observed, 171.63 expected, observed/expected ratio (o/e) 0.89, 90% interval 0.78 to 1.02.
Homologues: Orthologues: chimpanzee SLC7A11 (99% identical), macaque SLC7A11 (98% identical), pig SLC7A11 (93% identical), rabbit SLC7A11 (93% identical), dog SLC7A11 (92% identical), guinea pig SLC7A11 (92% identical), mouse Slc7a11 (89% identical), rat Slc7a11 (89% identical), tropical clawed frog slc7a11 (80% identical), zebrafish slc7a11 (69% identical), Drosophila melanogaster mnd (42% identical), Caenorhabditis elegans aat-1 (40% identical), and 10 more. Paralogues in human: SLC7A5 (44% identical), SLC7A6 (44% identical), SLC7A8 (43% identical), SLC7A7 (42% identical), SLC7A10 (42% identical), SLC7A9 (42% identical), SLC7A13 (27% identical), SLC7A4 (24% identical), SLC7A2 (24% identical), SLC7A1 (24% identical), SLC7A3 (23% identical), SLC7A14 (22% identical).
Diseases named in the same sentence as SLC7A11 in open-access papers:
SLC7A11 is named in the same sentence as 334 diseases in open-access papers, as found by Europe PMC text mining. Sharing a sentence is not in itself a finding about the gene and the disease. The quoted sentences say what the papers report.
breast cancer (185 papers, 2013 to 2026). A primary or metastatic malignant neoplasm involving the breast. "Higher SLC7A11 expression was associated with improved response to immunotherapy, but inferior prognosis in most tumors, including breast cancer." (PMID 42238600, 2026). "High SLC7A11 expression is associated with poor prognosis in several cancers, including acute myeloid leukemia, breast cancer, ovarian cancer, and colon cancer." (PMID 40764425, 2025). "Within the Breast Cancer Gene-Expression Miner dataset, SLC7A11 mRNA expression was significantly associated with higher tumor grade, lymph node negative tumors, and high NPI (all p ≤ .0005)." (PMID 38073087, 2024). "We, therefore, knocked down all five cullins (Cul-1, -2, -3, -4A, -4B, -5) individually, and found that only Cul-3 knockdown caused SLC7A11 accumulation in multiple breast cancer cell lines." (PMID 38959043, 2024). "Within the Breast Cancer Gene-Expression Miner dataset, high SLC7A11 was significantly associated with ER-, PR-, and HER2- BC (all p < .01)." (PMID 38073087, 2024). "A study ascertained that decreased SLC7A11 is associated with elevated methionine dependence in breast cancer cells." (PMID 35123415, 2022). "xCT is a multipass transmembrane protein encoded by the SLC7A11 gene, expressed at low levels in healthy tissues but highly expressed in several tumors, including all breast cancer subtypes." (PMID 36359363, 2022). "MiR-26b is downregulated in breast cancer cells, and treatment with miR-26b mimics downregulates SLC7A11 and causes apoptosis." (PMID 35755805, 2022). "The result showed that the ferroptosis-related gene SLC7A11 was higher in breast cancer tissues compared with normal tissues and associated with poor survival." (PMID 35252218, 2021). "In another study, SLC7A11-mediated glutamate export has been linked to the increased invasiveness of breast cancer cells." (PMID 33000412, 2021). "For example, SLC7A11 is associated with carcinogenesis, cancer stem cells (CSCs), and poor prognosis in breast cancer, and plays a role in recurrence, lymph node metastasis, and venous invasion in colorectal cancer." (PMID 34790572, 2021). "Breast cancer cell lines were selected based on expression of the gene encoding xCT (SLC7A11) using RT-qPCR, and xCT protein levels by western blot." (PMID 30190786, 2018). "The human homologue of bta-miR-26b was shown to play a protective role in the etiology of breast cancer by promoting apoptosis through targeting SLC7A11 while bta-miR-107 is associated with mammary stem cell activities." (PMID 30149509, 2018). "FXR deficiency may be a key factor for breast cancer cells to induce ferroptosis by regulating SLC7A11 expressions." (PMID 39543094, 2024). "Besides HB, overexpression of SLC7A11 is often associated with resistance to chemotherapy and radiotherapy in other types of cancers, including Burkitt's lymphoma, and breast cancers." (PMID 35604883, 2022). "Finally, SLC7A11 encodes a cystine/glutamate transporter that has been reported to suppress the expression of P-glycoprotein in breast cancer cells induced by ROS." (PMID 36133439, 2022). "SLC7A11 is associated with treatment resistance in breast cancer." (PMID 29562706, 2018). "However, the exact regulatory mechanism underlying the SLC7A11-mediated ferroptosis after IR in breast cancer remains unknown and needs further study." (PMID 35252218, 2021). "In breast cancer, mucin 1-C binds to the CD44 variant to stabilize the SLC7A11 molecule, while H3K9me2/3 on the Mucin 1-C promoter suppresses its transcription, thereby affecting GPX4’s capacity to induce ferroptosis." (PMID 40327848, 2025).
breast cancer (continued). "Our research revealed that estrogen/ERα signaling inhibits ferroptosis in ER+ breast cancer by upregulating the expression of SLC7A11 and SLC3A2." (PMID 39833180, 2025). "Mechanistically, increased H3K4me3 and decreased DNA methylation enhanced SLC7A11 transcription and cystine uptake in trastuzumab-resistant breast cancer." (PMID 40464376, 2025). "NRF2 knockdown had a pronounced effect on gene expression in MDA-MB-436 breast cancer cells, notably reducing multiple anti-ferroptosis genes, including SLC7A11, NQO1, TXNRD1, GCLM, and AKR1C1." (PMID 40867343, 2025). "SLC7A11 (xCT) in breast cancer regulates cystine/glutamate exchange, influencing ferroptosis and drug sensitivity, and in ovarian cancer, it is associated with cisplatin resistance via redox balance." (PMID 41425581, 2025). "Our research revealed that estrogen suppresses ferroptosis in ER+ breast cancer by increasing the expression of SLC7A11 and SLC3A2." (PMID 39833180, 2025). "Recent studies have shown that SLC7A11 is highly expressed in several tumor types, including lung cancer, breast cancer, colorectal cancer, and melanoma, and plays a pivotal role in the immune evasion mechanisms of tumors." (PMID 40012016, 2025). "In breast cancer, dihydroartemisinin enhances the radiosensitivity of breast cancer cells by inducing ferroptosis via the hsa_circ_0001610/miR-139-5p/SLC7A11 pathway." (PMID 40093329, 2025). "We further investigated the potential roles of the METTL3/SLC7A11 axis in vivo breast cancer progression." (PMID 39800682, 2025). "Metformin can inhibit the expression of the ubiquitin-like protein UFM1, which in turn suppresses the UFMylation of SLC7A11, leading to its reduced expression and induction of ferroptosis in breast cancer cells, thereby inhibiting cancer progression." (PMID 40374601, 2025). "A study focusing on the luminal A breast cancer subtype found that CDK4/6is reduces expression of the cystine transporter SLC7A11 by inhibiting SP1 binding to the SLC7A11 promoter region." (PMID 40244377, 2025). "SLC7A11 is highly expressed in various human cancers, including non-small cell lung cancer, breast cancer, colorectal cancer, liver cancer, pancreatic cancer, and melanoma." (PMID 40012016, 2025). "In general, trastuzumab primary-resistant HER2-positive breast cancer patients featured distinct amino acid metabolic patterns, especially increased plasma cystine levels and higher expression of SLC7A11." (PMID 40464376, 2025). "In breast cancer, metformin suppresses the UFMylation process of SLC7A11 to decrease its protein stability and induce ferroptosis in an AMPK-independent manner." (PMID 38705513, 2024). "Next, we validated the SNF2L/SLC7A11/GSH regulatory axis in patient-derived primary breast cancer cells." (PMID 39532848, 2024). "In breast cancer cells, hypoxia induces the expression of genes involved in the glutathione biosynthetic pathway, such as SLC7A11, which is a direct target gene of HIF1, and subsequently induces glutathione synthesis." (PMID 38547234, 2024). "In clinical breast cancer samples, we found elevated levels of SLC7A11 and USP18, and reduced levels of KCTD10." (PMID 40440083, 2024). "The IHC staining of human breast cancer tissues showed that in general, the SLC7A11 levels were positively correlated with USP18 levels, but negatively correlated with the KCTD10 levels in both nontumor and tumor tissues." (PMID 38959043, 2024). "Here, we reported that CRL3KCTD10 E3 ligase is responsible for SLC7A11 ubiquitylation in response to environmental cystine levels in breast cancer cells." (PMID 38959043, 2024).
breast cancer (continued). "Inhibition of SLC7A11 expression and methylation levels can increase lipid ROS levels and induce ferroptosis in breast cancer cells, thus inhibiting tumor growth." (PMID 38244591, 2024). "Circ_0000643 acts as a sponge for miR-153, enhancing SLC7A11 expression and inhibiting ferroptosis in breast cancer cells." (PMID 38994627, 2024). "The transporters SLC1A1, SLC7A1, and SLC7A11 are highly expressed in luminal subtypes of breast cancer and TNBC." (PMID 39852119, 2024). "The relationships between SLC7A11 mRNA expression and patient outcome were verified using Breast Cancer Gene-Expression Miner." (PMID 38073087, 2024). "Western blotting confirmed a dramatic reduction in SLC7A11 in primary breast cancer cells with SNF2L knocked down by shRNA." (PMID 39532848, 2024). "In our study, we found that the expression levels of FXR, vimentin and SLC7A11 were significantly higher in breast cancer tissues, particularly in metastatic cancer tissues compared to non-metastatic ones." (PMID 39543094, 2024). "Biologically, KCTD10 and USP18 confer breast cancer cells’ sensitivity or resistance to ferroptosis, respectively, via targeting SLC7A11." (PMID 38959043, 2024). "Detailed analyses in human breast cancer cells demonstrated that BAY mediated NRF2 nuclear translocation and increased HO-1 expression while cells deficient in SLC7A11 presented exacerbated ferroptosis." (PMID 38539832, 2024). "The distribution of SLC7A11 expression was unimodal and left-skewed and X-tile software was used to identify the optimal cutoff point in predicting breast cancer specific survival (BCSS)." (PMID 38073087, 2024). "On the other hand, hypoxia induces SLC7A11 gene expression by promoting hypoxia-inducible factor 1 (HIF-1) transcription factor activation in breast cancer." (PMID 39769017, 2024). "The SLC7A11 gene required for the proliferation of prostate cancer, breast cancer, renal carcinoma, and colon cancer cells, as has been shown, determines the high content of the light chain (SLC7A11 protein) of system xc– in the membranes of these tumor cells." (PMID 39125992, 2024). "The expression of SLC7A11 is dysregulated in many kinds of tumor cells, such as lung cancer, liver cancer, breast cancer and CRC, and plays an important role in the occurrence and development of tumor." (PMID 38774759, 2024). "In patients with HER2-enriched breast cancer with brain metastasis, the upregulation of xCT (SLC7A11), a cystine/glutamate antiporter facilitating cystine import and glutamate export, was observed." (PMID 38506114, 2024). "Therapeutically, the combination of MLN4924 with SLC7A11 inhibitor Erastin or its derivative IKE markedly enhanced the killing of breast cancer cells both in vitro and in vivo." (PMID 38959043, 2024). "The present study explored SLC7A11 expression in BC by assessing its genomic, transcriptomic, and proteomic levels for the first time in several large breast cancer cohorts." (PMID 38073087, 2024). "In fact, HIF-1 is a master regulator of cellular responses to hypoxia, and it can directly bind to the third intron of the SLC7A11 gene to activate its transcription after exposure to paclitaxel, a chemotherapy drug, in breast cancer cells." (PMID 39769017, 2024). "This delivery system was found to effectively suppress breast cancer bone metastasis via the synergistic function of sorafenib which suppresses SLC7A11, and photodynamic therapy induced by 660 nm laser which increases ROS level." (PMID 38705513, 2024). "Targeting SLC7A11 can inhibit the proliferation ability of various tumor cells such as colorectal cancer, breast cancer, and pancreatic cancer." (PMID 38811540, 2024). "For example, SLC7A11 was a risky factor for OS in breast cancer (BRCA) but a protective factor in colon adenocarcinoma (COAD)." (PMID 38420162, 2024). "Niclosamide is also a potent inhibitor of SLC7A11 in breast cancer cell lines, consequently leading to the induction of ferroptosis." (PMID 38891084, 2024).